ARID1A (AT-rich interaction domain 1A)
Diseases named in the same sentence as ARID1A in open-access papers (continued):
Sharing a sentence is not in itself a finding about the gene and the disease.
tumor (continued). "However, further investigations are required to address the mechanism of interaction between EBV and mutation in ARID1A to gain a better understanding of their combined effect in initiating/mediating tumor progression." (PMID 32325943, 2020). "ARID1A is one of the most frequently mutated tumor suppressor genes in various types of cancer." (PMID 33344089, 2020). "Similarly, a study by He et al79 suggested that ARID1A down‐regulation was markedly associated with HCC tumour growth, poor prognosis and overall metastasis, including local lymph node metastasis and distant metastasis, especially lung metastasis." (PMID 32162380, 2020). "Interestingly, we found that there was 50% and 66% of CCA with ARID1A mutation showed tumor stage IV and T3/T4, respectively." (PMID 33344089, 2020). "Consequently, there is a paradoxical phenomenon that, compared with ARID1A wild‐type tumours, their ARID1A‐mutated counterparts display remarkably less genomic instability, as measured by copy number alteration analysis across multiple cancer types." (PMID 32162380, 2020). "Inactivating mutations in ARID1A have been identified in a wide variety of malignancies, suggesting that it functions as a tumor suppressor." (PMID 33344089, 2020). "Interestingly, data pooled by a meta-analyses on colorectal and gastric cancer confirmed the presence of EBV infection as well as reported loss of ARID1A protein expression associated with advanced grade and tumor differentiation." (PMID 32325943, 2020). "However, the molecular mechanism by which ARID1A deficiency or mutation in HCC affects tumour development remains largely unclear." (PMID 32162380, 2020). "We were able to find a link to MSI-H and ARID1A loss in our cohort in only one tumour." (PMID 31906887, 2020). "Only one tumour revealed high microsatellite instability (MSI-H) with concomitant ARID1A loss." (PMID 31906887, 2020). "As a tumor suppressor, Arid1a is associated with the development, survival, and progression of cancer cells, and its dysfunction may be key tumorigenic events in ovarian, endometrial, gastric, and breast cancers." (PMID 32670021, 2020). "Furthermore, ARID1A loss/decrement is associated with aging, poor tumor differentiation, tumor size, tumor grade, and metastasis in human patients." (PMID 31238554, 2019). "Indeed, ARID1A-mutated cells display a higher level of basal apoptosis in vitro and ARID1A KO reduces tumor growth in vivo in an orthotopic xenograft model." (PMID 31492885, 2019). "As many in-frame ARID1A mutations impair its translocation to the cytoplasm and promotes its degradation by the proteasome, the loss of ARID1A tumor suppressor could also support oncogenesis." (PMID 31426393, 2019). "Additionally, altered expression of urothelial differentiation factors such as FOXA1 and loss of function mutations in chromatin remodeler proteins such as ARID1A are important in disease progression and contribute to tumor heterogeneity in BC." (PMID 31137849, 2019). "This may be another reason why ARID1A mutations are commonly observed alongside activating PI3K mutations in neoplasms originating from the endometrial epithelium." (PMID 31391455, 2019). "The significant correlations of ARID1A mutations with TMB and tumor aneuploidy levels may explain why ARID1A-mutated GI cancers have elevated immune activity compared to ARID1A-wildtype GI cancers." (PMID 31277418, 2019).
tumor (continued). "Overall, these findings indicate that the context in which ARID1A loss occurs likely determines whether it plays a primarily tumor suppressive or tumor promoting role." (PMID 31217031, 2019). "Our results showed that DNA purified by “liquid microdissection” from tumor tissue could be used to identify the exact prevalence of ARID1A mutations, which was found to be higher than that stated in previous reports." (PMID 29599905, 2018). "It has been additionally reported that dysregulation of the PI3K signaling pathway and loss of function of ARID1A may have a combination effect on tumor development." (PMID 30333046, 2018). "Based on the patterns of mutations in tumor cells, ARID1A likely functions as a tumor-suppressor." (PMID 29389935, 2018). "Mutations observed in ARID1A have been found in many tumor types including CRC." (PMID 29505855, 2018). "ARID1A mutations typically results in loss of protein function with implications for cell proliferation, differentiation and apoptosis – essential roles of a tumor suppressor gene." (PMID 29093822, 2017). "Using xenograft analysis, we provide evidence suggesting that ARID1A loss might be more potent in enhancing tumor growth than PBRM1 loss." (PMID 27764136, 2016). "Hence, mutations do appear to account for the loss of ARID1A in certain tumor types, as the abrogating mutation rates are comparable to the loss of expression for endometrial tumors as determined by IHC." (PMID 25774356, 2014). "The identification of an ARID1A mutation in tumor one in the contralateral kidney to those tumors harboring MTOR mutations may further illustrate convergence upon the PI3K-AKT-mTOR pathway." (PMID 25159823, 2014). "Truncating mutations in ARID1A were detected in 32% (7/22) of tumours." (PMID 25233892, 2014). "Interdependency on PI3K/AKT activation of ARID1A mutated tumor clones might be a process that is targetable by small-molecule inhibitors of the PI3K/AKT/mTOR pathway." (PMID 24036443, 2013). "Furthermore, it is likely that ARID1A mutations have divergent effects, depending on different cell and tumor types in which they are present, probably also depending on the mutational landscape in different cancer types." (PMID 24036443, 2013). "As a result, ARID1A mutations typically generate truncated proteins that are highly prone to degradation (Guan, unpublished result), a characteristic feature of classical tumor suppressors." (PMID 21614196, 2010). "Therefore, loss-of-function mutation in ARID1A may compromise the expression of many genes involved in tumor suppression, differentiation, Epithelial to Mesenchymal Transition (EMT), and lineage specificity, which subsequently leads to cancer progression." (PMID 41278204, 2025). "Importantly, the cancer hallmark of immune modulation seen in ARID1A mutant tumours can already be observed in pre-neoplastic tissue, suggesting ARID1A-deficient fields may predispose to cancer." (PMID 39920335, 2025). "Thus, RUNX3 may be a bona fide tumor suppressor in FL and be inactivated by several mechanisms, including 1p36 deletions and/or disruptive ARID1A mutations." (PMID 39843653, 2025). "Furthermore, tumors harboring ARID1A mutations may exhibit high microsatellite instability (MSI-H) or high tumor mutation burden (TMB), potentially rendering them responsive to immune checkpoint inhibitors such as pembrolizumab and nivolumab." (PMID 40281353, 2025). "However, the precise prognostic significance of ARID1A mutations in PDEECs may vary depending on the tumor subtype and the presence of coexisting mutations." (PMID 40072110, 2025).
tumor (continued). "Likewise, ARID1A mutations correlate with higher tumor mutational burden and may predict immunotherapy response, providing a potential guide for further development of subtype-tailored therapies." (PMID 41373802, 2025). "Therefore, ARID1A alterations caused by mutation and low expression might be essential in tumor progression." (PMID 41049615, 2025). "Finally, using publicly available clinical datasets from cBioPortal, tumours with low ARID1A, low PTEN, and high cFos were associated with a significantly poor survival outcome when compared to high ARID1A, high PTEN, and low cFos levels, corroborating the findings of our TMA analysis." (PMID 39885328, 2025). "Consequently, ARID1A-deficient tumor cells become more susceptible to CDK13 inhibitor treatment." (PMID 38835016, 2024). "While overexpression of ARID1A promoted tumor initiation, loss of ARID1A could be discovered in established tumor that degraded chromatin accessibility and downregulated expression of genes relative to tumor progression." (PMID 38405061, 2024). "We hypothesized that the loss of Arid1a increases the rate of tumor progression and metastasis." (PMID 39123453, 2024). "However, increasing evidence has shown that ARID1A deficiency may modulate the tumour immune system, correlating it with better therapeutic outcomes of ICBs." (PMID 38166741, 2024). "Moreover, the deletion of ARID1A in the tumor microenvironment activates cancer-associated fibroblasts and drives the proliferation and migration of lung cancer cells, but inhibits tumor cell autophagy and enhances the sensitivity of immunosuppressive therapy for EGFR-mutant lung adenocarcinoma." (PMID 38584203, 2024). "Additionally, whether the ARID1A variants we observed were acquired during tumor development or already present in the germline and thus related to cancer susceptibility besides response to treatment remains to be determines." (PMID 37182128, 2023). "However, in established liver tumors, Arid1a loss promotes tumor progression and metastasis." (PMID 36980292, 2023). "Indeed, ARID1A mutations occur in many human cancer types and result in limited chromatin accessibility and downregulation of interferon-responsive genes, leading to poor tumor immunity." (PMID 37770710, 2023). "A recent large study indicated that ARID1A mutational status could be predictive biomarker for indication of favourable response to 5-FU chemotherapy combined with PD-1 inhibitors in patients with high tumour mutational burden and MSI status." (PMID 37568604, 2023). "In addition, ARID1A mutation is associated with increased expression of PD-L1, which reduces the level of antitumor immune response and may promote immune escape of tumor cells." (PMID 37981695, 2023). "Therefore, AKT inhibitors have the potential to be effective in ARID1A‐deficient tumours." (PMID 38041544, 2023). "However, it is possible that mutations in the SWI/SNF family, particularly ARID1A mutations that co-occur in high TMB tumours, are bystander mutations of the high TMB/MSI mutation phenotype, and thus, may not be causally related." (PMID 37821580, 2023). "In addition, ARID1A expression loss could endow tumor cells with an EMT phenotype and metastatic ability." (PMID 36869329, 2023). "Recent studies have evidenced that ARID1A mutations are predominantly subclonal, heterogeneous and may alter the epigenetic landscape to foster cancer cell dissemination of already established tumours." (PMID 35167193, 2022). "Thus, ARID1A deficiency due to somatic mutations propels tumor progression and dissemination." (PMID 36123603, 2022).
tumor (continued). "We also found that TAMs and cytotoxic T cells were also excluded from the vicinity of tumour cells in ARID1A-mutated OCCCs compared to ARID1A wild-type tumours, suggesting that the exclusion of these immune effectors could determine the host response of ARID1A-mutant OCCCs to therapy." (PMID 34359755, 2021). "However, the current report found a significant correlation between loss of ARID1A expression and primary colon and metastases cancer stages, suggesting that loss of ARID1A expression may drive tumor formation, invasion, and tumor differentiation." (PMID 34414106, 2021). "In addition to these molecular differences, the most striking immunohistochemical differences between solid and glandular areas were the complete loss of SMARCA4 in the solid component in one tumor and the focal loss of ARID1A in the undifferentiated area of two tumors." (PMID 33435234, 2021). "It suggested ARID1A serves as the downstream molecule of this pathway, NF-κB firstly stimulates the miR-223-3p expression which could directly bind to ARID1A and then influences the proliferation and migration of tumor cells through the function loss of ARID1A." (PMID 34715776, 2021). "Besides, researchers suggested that the tumor cells harboring ARID1A alterations showed the therapeutic sensitivity to Bcl-2 inhibitors which indicated the activation of apoptotic pathways induced by ARID1A alterations or expression loss." (PMID 34715776, 2021). "Thus, ARID1A mutated tumors especially with elevated PD-L1 levels, microsatellite instability-high and high tumor mutational burden could be good candidate to anti-PD-1/PD-L1 immunotherapy as demonstrated by a very recent report." (PMID 32987854, 2020). "Therefore, ICI treatment may change the metabolism of tumor cells and T cells and relieve the inhibition of the antitumor effect of T cells, which allows patients with ARID1A and PIK3CA mutations to gain clinical benefits." (PMID 33363171, 2020). "Thus, in contrast to the defective DNA repair that appears to be at least partially responsible for restraining neoplastic progression within the pancreatic epithelium, impaired MMR in the setting of ARID1A loss appears to be a tumor neutral phenomenon that persists in the autochthonous lines." (PMID 32967217, 2020). "Thus, we hypothesized that ARID1A mutation status may be involved in an anti-tumor effect of WHSC1 suppression similar to EZH2." (PMID 31092221, 2019). "Additionally, heterozygous loss of ARID1A may promote metastasis at late stages of the tumor progression, as observed in liver cancer." (PMID 31391455, 2019). "We investigated the correlation between ARID1A mutations and tumor immunity using three GI cancer genomics datasets by the bioinformatic approach, and found that diverse antitumor immune signatures were more highly enriched in ARID1A-mutated GI cancers than in ARID1A-wildtype GI cancers." (PMID 31277418, 2019). "We next assessed whether the clinical ATRi, VX-970, could inhibit ARID1A-deficient tumours in vivo." (PMID 27958275, 2016). "While 30% of ARID1A mutations in the literature affect both alleles, 73% of the cases lack protein expression, implicating that haploinsufficiency for ARID1A may be enough to promote tumor formation." (PMID 27590521, 2016). "Thus, the assessment of BAF250a by IHC may be preferable to sequencing ARID1A in tumor samples to identify associations with AKT signaling." (PMID 24559118, 2014). "We find that 11.5% of all UBC harbor ARID1A pathogenic mutations, most of them truncating, and that multiple gene mutations can be found in some of the tumors/cell lines, supporting biallelic inactivation or intratumoral heterogeneity, as has been reported in other tumor types." (PMID 23650517, 2013).
tumor (continued). "We therefore analyzed whether ARID1A loss of expression is associated with epithelial differentiation markers in UBC that have - in turn -been related to the genetic pathways involved in this tumor." (PMID 23650517, 2013). "Combining both studies, two mutations were identified in the same tumor in 30% of the mutated cases, which, taken together with the inactivating nature of the mutations and their remarkable frequency, provided unequivocal evidence that ARID1A is a tumor suppressor gene in these two tumor types." (PMID 22009941, 2012). "Collectively, our findings define ARID1A as a crucial tumor‐suppressor gene in BC via its collaboration with CEBPα." (PMID 41459628, 2026). "Hepatocyte‐specific ARID1A knockout mice exhibit F4/80+ macrophage and CD11c+ neutrophil infiltration in tumour margins, concomitant with IL‐6/TNF‐α hyperproduction and NF‐κB/STAT3 pathway activation." (PMID 41578412, 2026). "ARID1A‐mutant tumours, for instance, display heightened sensitivity to inhibition of ATR and several additional targets." (PMID 41537447, 2026). "Mechanistically, ARID1A depletion in tumor cells interrupts the competitive binding of ARID1A to YAP, causing excessive YAP activation and transcriptionally increasing the expression of polyamine metabolic enzymes, thereby enhancing polyamine synthesis." (PMID 41951577, 2026). "Together, these findings highlight aberrant cell types, states, and cell‐cell interactions in Arid1a‐deficient liver under AAI stimulation, potentially driving inflammation, fibrogenesis, and tumor progression." (PMID 41133886, 2026). "Classic examples include PARPis in BRCA1/2‐deficient tumours and EZH2 inhibition in ARID1A‐deficient cancers." (PMID 41537447, 2026). "ARID1A, a tumor suppressor gene located on chromosome 1p36.11, is part of the chromatin-regulating SWI/SNF complex whose subunits are altered in 20% of cases across all tumor entities." (PMID 42122122, 2026). "The nuclear expression of ARID1A has been negatively associated with tumor size, pathological grade, tumor recurrence, and survival in human HCC patients, while somatic mutations in ARID1A have been reported in HCC." (PMID 41522204, 2026). "In four patients, longitudinal analysis of subsequent lesions highlighted an increase in mutations, like missense or splice variants in the PMS2, SMARCA4, ARID1A, AKT1, BMPR1A, and PTEN genes, suggesting tumor evolution." (PMID 41514647, 2025). "We further investigate cFos and JUND protein levels in the murine tumours with varying Arid1a status." (PMID 39885328, 2025). "By enabling DNA repair, regulating cell cycle checkpoints, and maintaining epigenetic stability, ARID1A acts as a tumor suppressor." (PMID 41514650, 2025). "In TNBC, loss-of-function mutations or downregulation of ARID1A disturb cell cycle regulation and DNA repair, increase EMT, and activate the PI3K/AKT pathway, forcing aggressive tumor proliferation and resistance to treatments." (PMID 41514650, 2025). "The recent review discussed the dual role of ARID1A as a suppressor gene and as an initiator of tumor progression." (PMID 39796161, 2025). "Conversely, progesterone receptor (PR) was negative in the only tested case, as well as GATA-3, SALL-4, PTEN, PAX-2, AFP and calretinin, while ARID1A was retained in one case and another tumor has a CK7+/CK20− phenotype." (PMID 39996865, 2025). "Molecular mechanisms related to the tumor suppressor role of ARID1A seem to be distinct among different cancerous tumors." (PMID 41049615, 2025).